TSBP1-AS1 (TSBP1 and BTNL2 antisense RNA 1)
Synonyms: XXbac-BPG154L12.4; dJ1077I5.3; HCG23
Gene: Long non-coding RNA gene on chromosome 6 (32,254,640 to 32,407,763, forward strand). Ensembl gene ENSG00000225914.
Diseases named in the same sentence as TSBP1-AS1 in open-access papers:
TSBP1-AS1 is named in the same sentence as 3 diseases in open-access papers, as found by Europe PMC text mining. Sharing a sentence is not in itself a finding about the gene and the disease.
TSBP1-AS1 shares sentences with these, for which no sentence is quoted: adenocarcinoma of the lung (1 paper); asthma (1); lung diseases (1).